JAK1 (Janus kinase 1)
Diseases named in the same sentence as JAK1 in open-access papers (continued):
Sharing a sentence is not in itself a finding about the gene and the disease.
lung cancer (48 papers, 2012 to 2026). A malignant neoplasm involving the lung. "Our studies with the OncoImmune PPI and HTiP approaches uncovered IAP and IAP-regulated JAK1-STING innate immunity pathway as an immune-dependent vulnerability in LKB1 mutated lung cancer cells for overcoming the immunotherapy resistance." (PMID 40057483, 2025). "In lung cancer, tumor growth and patient survival is closely linked to the IL-10/JAK1 axis activation." (PMID 32477352, 2020). "JAK1 has been implicated in the progression of several human cancers, including lung cancer." (PMID 39209829, 2024). "JAK1-deficient or mutant cell lines show greater tumorigenicity, which has been reported in patients with hepatocellular carcinoma, acute lymphoblastic leukemia, lung cancer, and gastric cancer." (PMID 33323549, 2020). "Here we report the identification of the Liver Kinase B1 (LKB1)-Inhibitor of Apoptosis Protein (IAP)- Janus Kinase 1 (JAK1) dynamic complex as a molecular determinant for immune response of LKB1-mut lung cancer cells." (PMID 40057483, 2025). "To assess the effect of JAK on PI3K/AKT signaling, we administered different doses of ruxolitinib, a selective JAK1/2 inhibitor, to three lung cancer cell lines." (PMID 39209829, 2024). "In vitro studies showed that leptin enhanced production of soluble intercellular adhesion molecule-1 (ICAM-1) in lung cancer cells through triggering a signaling cascade involving JAK1/2, STAT3, FAK, ERK, and GSK3αβ." (PMID 38571500, 2024). "Targeting specific proteins such as SRC, STAT3, PIK3CA, MAPK1, EGFR, and JAK1 is crucial for impeding the growth of lung cancer." (PMID 38921583, 2024). "Upregulation of Rab1a expression in lung cancer cells enhances cell mobility including migration, invasion and metastasis both in vitro and in vivo through activating JAK1/STAT6 signaling pathway in an IL-4Rα dependent manner." (PMID 38695990, 2024). "Together, these data demonstrate that JAK1/STAT3 signaling is activated in IL20RB-expressing lung cancer cells by osteoclast-secreted IL-19." (PMID 36006737, 2022). "Here, we reported that Anwulignan suppresses non‐small cell lung cancer growth by directly targeting JAK1 in vitro and in vivo." (PMID 33523587, 2021). "The M2 macrophages secrete IL-10 in the extracellular media which binds to the IL-10RA, causing the activation of JAK1, STAT1, STAT3, STAT6, NF-κB, and Notch in lung cancer cells." (PMID 32477352, 2020). "The result revealed that the expression levels of JAK1 were lower in lung cancer tissues than in normal lung tissues." (PMID 33323549, 2020). "AZD1480 (a JAK1/2-TKI) impaired tumor growth in an EGFR-driven lung cancer mouse model and blocked growth of xenografted solid tumor cells." (PMID 32365499, 2020). "We showed that forced miR‐206 expression restored gefitinib sensitivity in IL6‐induced gefitinib‐resistant EGFR‐mutant lung cancer cells by inhibiting IL6/JAK1/STAT3 pathway." (PMID 31507089, 2019). "Together, these data demonstrate that Ntrk1 expression can modulate KP lung cancer biology as well as the immune microenvironment via Jak1 signaling to promote the expression of immunosuppressive molecules including PD-L1." (PMID 30986992, 2019). "Recently, HHT has been shown to induce apoptosis and suppress STAT3 via IL-6/JAK1/STAT3 signal pathway in Gefitinib-resistant lung cancer cells." (PMID 29788973, 2018). "Because the inhibition of JAK1/STAT3 signaling exhibits potent tumor-suppressive effects on lung cancer, it is important to study how IL10 induces JAK1/STAT3 signaling in cancer development." (PMID 26956044, 2016). "Whereas it was found STAT3 acted as a JAK1/JAK2-induced oncogenic driver in lung cancers, STAT1 expression was reported to form part of a genetic signature predicting event-free and overall survival of lung cancer patients." (PMID 24833526, 2014).
lung cancer (continued). "Lung cancers often carry constitutively active tyrosine phosphorylated STAT3 (abbreviated as pSTAT3) induced by JAK1 or JAK2 and the JAK2-STAT3 signaling node is a major oncogenic driver in lung tumors." (PMID 24833526, 2014). "Pathway analysis revealed that JAK1 was the final target gene for the sensitivity to enzastaurin in lung cancer cells." (PMID 22333600, 2012). "Pathway analysis revealed that JAK1 was an important gene for the sensitivity to enzastaurin in lung cancer cells." (PMID 22333600, 2012). "However, our findings at the protein level of JAK1/2 as poor prognostic markers support findings from other tumour types, including ovarian, non‐small cell lung cancer and pancreatic cancer." (PMID 37199043, 2023). "To validate this hypothesis, we performed dual-immunofluorescence staining for MUC1-CT and p-JAK1 to examine whether these two proteins co-localise in lung cancer cells." (PMID 36810913, 2023). "In contrast, JAK1 has been suggested to activate STAT3 activity in lung cancer cell lines." (PMID 26843613, 2016). "Initial studies determined whether MMF interacted with the JAK1/2 inhibitor ruxolitinib to kill lung cancer cells." (PMID 26981780, 2016). "In lung cancers JAK1 and JAK2 induce oncogenic signaling through STAT3." (PMID 24833526, 2014). "In addition, Rab1A is found to be a determinant sensitivity of JAK1 inhibitor, suggesting that JAK1 inhibitor could be potential therapeutics for lung cancer metastasis." (PMID 38695990, 2024). "Among all the tested genes, the top-performing ones were NUMA1 and JAK1 in KIRC, PDGFRB and BCL6 in lung cancer, IRS2 in endometrial cancer, and GNAS in BRCA, each with an AUC of at least 0.89." (PMID 38491101, 2024). "A significant body of evidence points to the importance of upstream regulators of STAT3 in lung cancer development, for example, EGFR and Src,34 our study highlights JAK1 as a candidate kinase for STAT3 phosphorylation and activation in LUSC." (PMID 39099000, 2024). "Collectively, our results highlight the new molecular mechanisms of AICAR that target MUC1-CT and its interactions with EGFR and JAK1 and provide a new therapeutic approach against EGFR-mutant lung cancer." (PMID 36810913, 2023). "AICAR represses the MUC1 activity in EGFR-mutant lung cancer, disrupting protein–protein interactions between MUC1-CT and JAK1 and EGFR." (PMID 36810913, 2023). "EGFR is highly expressed in a variety of malignant tumors, and its receptor dimerization can activate JAK1 and STAT, thereby regulating the cell cycle and apoptosis of lung cancer cells." (PMID 35190747, 2022). "In this study, A549 lung carcinoma cells exposed to PM10 showed increases of IL-6 and phosphorylation of JAK1/JAK2/STAT3 signaling molecules." (PMID 33374928, 2020). "MSI is rare in other tumor types such as lung cancer; however, 17% (29/173) of other tumors that were MSI-H also had a JAK1 frameshift." (PMID 29121062, 2017). "As a previous study indicated that JAK1 is the critical JAK kinase contributing to STAT3 activation and mediates IL-6-induced STAT3 activation in lung cancer cells, we next determined the effect of NOX4 overexpression on JAK1/STAT3 activity in A549 cells." (PMID 25504436, 2015). "Myricetin was found to directly bind to Jak1 and has been reported to prevent the phosphorylation of STAT1 and inhibit both the expression and nuclear translocation of IRF1 to suppress IFN-γ-induced IDO1 expression in human lung cancer cells." (PMID 40002369, 2025). "Similarly, in lung cancer, afatinib-induced STAT3 activation reduces drug sensitivity, which can be reversed by inhibiting IL-6R/JAK1/STAT3 signaling." (PMID 40999385, 2025). "Further, AXL expression was associated with JAK1-STAT3 signaling in treatment-naïve tumors and lung cancer patient-derived organoids with high levels of AXL and JAK1 were sensitive to combined treatment with AXL kinase inhibitor TP-0903 and JAK inhibitor ruxolitinib." (PMID 34830794, 2021).
lung cancer (continued). "Similarly, ruxolitinib (another JAK1/2-TKI) had a promising preclinical profile by potently blocking tumor growth in EGFR- and K-RAS-driven lung cancer models and restoring cisplatin-sensitivity to resistant NSCLC cell lines." (PMID 32365499, 2020). "Expressions of JAK1,2,、 STAT3 、PD-L1 and ATM were increased in A549CisR and H157CisR cells and could by induced by cisplatin in parental lung cancer cells." (PMID 30961670, 2019). "In addition, PLOD3 knockdown is expected to downregulate JAK1; therefore, we consider that the JAK-PLOD3-STAT3 axis plays an important signaling role in PLOD3-induced lung cancer metastasis." (PMID 30442941, 2018). "Furthermore, in vivo and in vitro studies have discovered that lung adenocarcinoma A549 cells induce OCs to secrete the ligand IL-19 for IL-20RB, activating the downstream JAK1/STAT3 signaling pathway, and promoting lung cancer proliferation in the bone microenvironment." (PMID 38571500, 2024). "It is not clear if MUC1 interacts with JAK1 directly in lung cancer." (PMID 36810913, 2023). "Besides JAK1, mutant EGFR mediates MUC1-CT expression in the transgenic lung cancer mouse model." (PMID 36810913, 2023). "To further elucidate whether ATM downregulates PD-L1 via JAK1,2/STAT3 pathway, we generated ATM-overexpression A549CisR and H157CisR cells (A549CisR-ATM and H157CisR-ATM) and confirmed that ATM-overexpression increased the expression of PD-L1 expression in lung cancer cells." (PMID 30961670, 2019). "However, our immunoblotting analysis showed that the expression of JAK1, JAK2 and PKC was not significantly altered when HDAC7 expression was depleted in human lung cancer cell line H1299." (PMID 29126425, 2017).
myeloproliferative neoplasm (45 papers, 2012 to 2025). A clonal hematopoietic stem cell disorder, characterized by proliferation in the bone marrow of one or more of the myeloid (i.e., granulocytic, erythroid, megakaryocytic, and mast cell) lineages. "JAK-targeted therapies, such as the first-in-class JAK1/2 ATP competitive inhibitor ruxolitinib, were introduced a decade ago for the treatment of myeloproliferative neoplasms (MPN) driven by JAK/STAT signaling activating mutations in JAK210, CALR11 or MPL12." (PMID 40623967, 2025). "Inhibition of this pathway via JAK inhibitors (JAKinibs) is therefore an attractive therapeutic strategy underlined by Ruxolitinib (JAK1/2 inhibitor) being approved for the treatment of myeloproliferative neoplasms." (PMID 34073410, 2021). "The discovery of the Jak2V617F somatic mutation in myeloproliferative disorders triggered the rapid development of Jak1/2-specific inhibitors for a variety of myeloproliferative and auto-immune disorders as well as hematological malignancies." (PMID 34680353, 2021). "Inhibition of the constitutively activated JAK/STAT pathway in JAK2V617F mutated cells by the JAK1/JAK2 inhibitor ruxolitinib resulted in clinical benefits in patients with myeloproliferative neoplasms." (PMID 29228564, 2017). "Selective JAK1/2 small-molecule inhibitors that have been developed to treat JAK- mutated myeloproliferative disorders are currently in clinical trials for a variety of cancers." (PMID 23056499, 2012). "Moreover, while JAK1–3 are associated with inflammatory diseases, JAK1 and 2 signaling, are more strictly connected to malignancies, including myeloproliferative neoplasms." (PMID 35337171, 2022). "The pathogenetic impact of this variant is well established in a murine bone marrow transplantation model in which T618I is sufficient to generate a lethal myeloproliferative disorder with neutrophilic expansion sensitive to JAK1/2 inhibition." (PMID 39907800, 2025). "Ruxolitinib is a JAK1/2 inhibitor used to treat patients with myeloproliferative disorders as well as acute and chronic graft-versus-host disease after stem cell transplants." (PMID 40569692, 2025). "Ruxolitinib is widely indicated for the treatment of the myeloproliferative neoplasms (MPNs) via inhibition of dysregulated janus kinases (JAK1 and JAK2) despite the side effects such as thrombocytopenia, anemia, and neutropenia." (PMID 34445192, 2021). "Janus kinase 1 and 2 (JAK1/2) inhibitors represent an emerging and promising pharmacological class of anticancer drugs used notably for the treatment of some myeloproliferative neoplasms." (PMID 34067242, 2021). "In line with our observations, Ruxolitinib, an FDA-approved inhibitor of upstream STAT3 activating JAK1/2 kinases, enhanced sensitivity of myeloproliferative neoplasms to PARPi treatment." (PMID 34956861, 2021). "Ruxolitinib is a novel biologic agent used for the treatment of myeloproliferative diseases, that inhibits Janus kinase 1 (JAK1) and Janus kinase 2 (JAK2)." (PMID 33413168, 2021). "Ruxolitinib, a selective JAK1/2 inhibitor approved by the FDA for myeloproliferative neoplasms, is being studied in relapsed B-cell lymphoma and PTCL (NCT01431209)." (PMID 32188095, 2020). "The role of JAK2 inhibitors like ruxolitinib and fedratinib has been studied in patients with myelofibrosis and myeloproliferative neoplasms (MPNs) that consistently exhibit dysregulation of the JAK1/JAK2 pathway." (PMID 29515770, 2018). "Ruxolitinib is a potent and selective JAK1/JAK2 inhibitor, with activity against myeloproliferative neoplasms (MPNs) including those harboring the JAK2V617F mutation." (PMID 29515770, 2018). "Very similar results were obtained by using the Jak1/Jak2 inhibitor ruxolitinib clinically in use for myeloproliferative neoplasms." (PMID 27286446, 2016). "The recent JAK1/2 inhibitor trial in myeloproliferative neoplasms (MPNs) showed that reducing inflammation can be more beneficial than targeting gene mutants." (PMID 26491227, 2015).
myeloproliferative neoplasm (continued). "The JAK/STAT pathway is constitutively activated in myeloproliferative neoplasms and can be inhibited by ruxolitinib, a selective JAK1/2 inhibitor." (PMID 26356819, 2015). "The JAK1/2 inhibitor ruxolitinib has been used to prevent Stat5 activation in patients with myeloproliferative neoplasms (MPN)." (PMID 24276378, 2013). "AZD1480 is a potent small-molecule JAK1/2 inhibitor that is under phase I clinical trials for the treatment of myeloproliferative diseases." (PMID 23056499, 2012). "Another potent JAK1/2 inhibitor, momelotinib, has been used to treat myeloproliferative neoplasms." (PMID 32086862, 2020). "JAK mutations, particularly those affecting JAK1 and JAK2, are oncogenic in both acute lymphoblastic leukemia (ALL) and myeloproliferative neoplasms (MPN)." (PMID 40470252, 2025). "Ruxolitinib is an FDA-approved JAK1/2 inhibitor for myeloproliferative neoplasms (MPN) and steroid-refractory acute graft-versus-host disease (GVHD)." (PMID 37864230, 2023). "Whether JAK1/2 inhibitors should be continually administered close to the start of conditioning therapy is being investigated in the ongoing trials by the Myeloproliferative Disorders Research Consortium (NCT01790295) and the Fred Hutchinson Cancer Research Center (NCT02251821)." (PMID 27840748, 2016). "Ruxolitinib is a novel potent biologic agent that inhibits Janus kinase 1 (JAK1) and Janus kinase 2 (JAK2), reserved for patients with myeloproliferative diseases." (PMID 38576050, 2024). "This sensitized for treatment with the JAK1/JAK2 inhibitor ruxolitinib, which is approved for the treatment of myeloproliferative neoplasms and was shown to penetrate the blood–brain barrier in mice." (PMID 37495858, 2023). "In line with JAK-STAT pathway activation, efficacy of the JAK1/2 inhibitor ruxolitinib has been demonstrated in case reports and a clinical trial for patients with CNL and atypical CML, a related myeloproliferative disorder." (PMID 35200567, 2022). "Ruxolitinib is the first janus kinase 1 (JAK1) and JAK2 inhibitor that was approved by the United States Food and Drug Administration (FDA) agency for the treatment of myeloproliferative neoplasms." (PMID 33589712, 2021). "Ruxolitinib is an orally available and potent selective inhibitor of JAK1 and JAK2, and it is the most advanced JAK1/JAK2 inhibitor in development for the treatment of myeloproliferative neoplasms." (PMID 26316489, 2015). "JAK1/2 inhibitors have been given to patients with myeloproliferative diseases for many years without significant infectious complications." (PMID 37744381, 2023). "JAK2/STAT signaling participates in the Ph-negative myeloproliferative neoplasms (MPN) pathophysiology and has been targeted by ruxolitinib, a JAK1/2 inhibitor." (PMID 31289316, 2019). "Despite the fact that hyperactive STAT1 signaling is linked to the expansion of abnormal megakaryocytes in myeloproliferative neoplasm (MPN), inhibiting STAT1 tyrosine phosphorylation with the JAK1/2 inhibitor Ruxolitinib has no influence on megakaryocytic differentiation." (PMID 31248103, 2019).